PROX1 (prospero homeobox 1)
Diseases named in the same sentence as PROX1 in open-access papers (continued):
Sharing a sentence is not in itself a finding about the gene and the disease.
Obesity (29 papers, 2015 to 2025). Accumulation of substantial excess body fat. "SUMOylation of Prox1 functions as a nutrient-sensitive switch that declines during fasting but is blunted in obesity, and hepatocyte-specific knock-in of a SUMO-deficient Prox1 lowers systemic cholesterol." (PMID 41373704, 2025). "PROX1 expression dysregulation in LECs causes lymphatic vasculature malformations that lead to lymphedema and are associated with obesity and metabolic diseases." (PMID 38203852, 2024). "In fact, Prox1 haploinsufficient mice, which survive to adulthood despite anatomical and functional lymphatic anomalies, exhibit obesity, an underlying risk for metabolic syndrome." (PMID 36111337, 2022). "In fact, these authors generated a Prox1 conditional knock‐out mouse and found that functional inactivation of a single Prox1 allele led to adult‐onset obesity due to abnormal lymph leakage from mispatterned and ruptured lymphatic vessels." (PMID 32757260, 2020). "Several studies in humans have now linked PROX1 expression to the development of hyperlipidemia, obesity, and T2D." (PMID 32477160, 2020). "Prox-1 haploinsufficiency causes lymphatic dysfunction and leads to adult-onset of obesity, in those mice, lymphatic restoration rescues them from the development of obesity." (PMID 31798464, 2019). "Our observations suggest that the PROX1 variants have pleiotropic effect on disease pathways and it seem to be a very interesting goal of research on prevention of obesity and type 2 diabetes mellitus." (PMID 25601634, 2015). "In addition to its role in obesity, PROX1 has also been linked to glycemic alteration (fasting glucose and type 2 diabetes) —another important feature of PCOS." (PMID 35144605, 2022). "Interestingly, the Prox1 gene seems to be associated with human obesity and type 2 diabetes mellitus (T2DM) in clinical studies." (PMID 36506056, 2022). "Prox1 has also been associated with obesity related to lymphatic dysfunctions in mice." (PMID 32757260, 2020). "Additionally, a single nucleotide polymorphism (SNP) in the Prox1 gene is associated with obesity and type 2 diabetes in humans, suggesting that lymphatic dysfunction may contribute to obesity and its metabolic complications." (PMID 36869026, 2023). "Similarly, the Prox1 gene is linked with lacteal integrity resulting in obesity." (PMID 36506056, 2022). "Lymph leakage has been previously shown to promote de novo adipogenesis in the Prox1+/– mice, leading to obesity in adulthood." (PMID 35663931, 2022). "VEGF-C signaling, the transformation of zipper-to-button junctions, and Prox1 have been confirmed to be related to obesity." (PMID 36506056, 2022). "In this context, deletion of the transcription factor Prox-1 (prospero homeobox-1) in lymphatic endothelial cells in a mouse model led to the leakage of lymph, stimulating adipocytes to store fat and enhancing adult-onset of obesity." (PMID 36675759, 2022). "Five differentially methylated regions were in genes previously found to be associated with obesity and altered metabolic states (TRAP1, SLC38A3, PROX1, ALDH1B1, and FAM96A)." (PMID 36474183, 2022). "The inactivation of PROX-1 in mice results in changes in the structure of lymphatic vessels, which are leakier and lead to obesity in adulthood." (PMID 34564157, 2021). "Although most Prox1+/- pups die shortly after birth, some can survive to adulthood and show adult-onset obesity." (PMID 32640757, 2020). "In Prox1 heterozygous mice, lymphatic malfunction resulted in lymph leakage and accumulation of adipose tissue, culminating in adult-onset obesity." (PMID 32256375, 2020). "In humans, several studies have shown reduced PROX1 expression in hyperlipidemia, obesity, and type 2 diabetes patients." (PMID 32640757, 2020). "These Prox1+/− mice develop adipocyte hypertrophy (increase in the size of adipocytes), increased serum free fatty acids, fatty liver and obesity in adulthood." (PMID 32038308, 2020).
Obesity (continued). "Together these results suggest that leakage of lymph triggers the onset of adipogenesis and obesity in Prox1+/− mice." (PMID 32038308, 2020). "The studies show that Prox1 ± mice, which have very leaky visceral lymphatics, accumulate a significant amount of abdominal visceral fat such that they develop obesity in their adulthood." (PMID 31866877, 2019). "A recent study indicates that repairing the leaky lymphatics in Prox1 ± mice prevents them from becoming obese, further confirming that the leaky lymphatics are responsible for their obesity phenotype." (PMID 31866877, 2019). "We also identified six DMRs which mapped to obesity and related metabolic traits in the GWAS catalogue (PROX1, PHACTR1, SLC22A8, SMAD3, LCAT, DNM2)." (PMID 25651499, 2015). "In another genome-wide association study, body mass index and waist circumference were strongly correlated with SNPs in the Prox1 gene from 1049 Mongolian individuals, revealing that the 1q32 and 10q11.22 loci near the Prox1 gene were new candidate loci for obesity." (PMID 36506056, 2022). "Of these genes, four (TRAP1, SLC38A3, PROX1, and FAM96A) have also been associated with obesity and altered metabolic states, indicating that they may be implicated in differential progression of lean versus obese NASH-HCC." (PMID 36474183, 2022). "Whether PROX1 regulates CPT1a expression in other tissues, and whether this pathway could contribute to the onset of obesity in Prox1+/− mice needs to be evaluated." (PMID 32038308, 2020). "Importantly, in vivo restoration of the Prox1 level, specifically in the lymphatic endothelial cell, was sufficient to reverse the lymphatic defects in Prox1± mice and ameliorate their obesity phenotype." (PMID 32256375, 2020). "Hence, it is possible that obesity arises in Prox1+/− mice as a consequence of metabolic defects in multiple tissues as reported for another transcription regulator TRIM28." (PMID 32038308, 2020). "Specifically, previous studies have found that SNPs within Cdh23 were correlated with BMI, SNPs in Tph2 were correlated with obesity, SNPs in Prox1 were correlated with glucose metabolism, SNPs in Lipc were correlated with cholesterol, and SNPs in Pnpla3 were correlated with hepatic lipid content." (PMID 31262088, 2019). "Finally, it seems that the PROX1-related pathways are the very interesting goal of research on prevention of obesity and type 2 diabetes mellitus." (PMID 25601634, 2015). "When the multivariate generalized linear model was used, the PROX1 CC genotype was associated with VAT/SAT ratio [OR 1.5 (1.01–2.3), p = 0.041] adjusted for age, gender, BMI, fasting insulin, diet and/or treatment of obesity." (PMID 25601634, 2015). "Interestingly, the SNPs of Prox1 showed a solid relation to obesity and T2DM in a human study." (PMID 36506056, 2022). "However, conditional deletion of one allele of Prox1 using lymphatic vasculature-specific Lyve1-Cre in a non-NMRI background does not result in obesity." (PMID 32038308, 2020). "Our study showed that several risk variants for obesity or metabolic diseases (FTO rs1121980, KCNQ1 rs163182, MC4R rs12970134, and PROX1 rs340841) were also associated with GDM, giving further evidence that GDM and obesity/metabolic diseases may share a similar genetic background." (PMID 32390949, 2020). "Hence, it is possible that the adipocyte inflammation observed in Prox1+/− mice might be contributing to the onset of obesity in older mice." (PMID 32038308, 2020). "Hence, whether increased plasma insulin levels might contribute to obesity in Prox1+/− mice could be investigated." (PMID 32038308, 2020). "Hence, it is worth investigating whether PROX1 might be playing additional LEC-independent roles in regulating obesity." (PMID 32038308, 2020).
Obesity (continued). "Importantly, the development of obesity was directly linked to LEC maintenance of Prox1 expression in this model as conditional, endothelial cell-Prox1 + /− mice similarly were characterized by impaired lymphatic vascular function and the development of obesity." (PMID 32477160, 2020). "Our lab is currently seeking answers to these important questions, in the context of obesity and metabolic syndrome, in PAI-1fx/fx mice crossed to Lyve1, Prox1, or Myh11 Cre-lines." (PMID 35308249, 2022). "Interestingly, although the most common clinical cause of obesity is over-nutrition rather than genetic abnormalities, recent genome-wide association studies have identified single-nucleotide polymorphisms in the Prox-1 that are linked with increased waist circumferences and obesity." (PMID 32499718, 2020). "This relationship was first documented by the observation that mice lacking Prox1 display adult-onset obesity, increased adiposity, and elevated lipid levels and that restoration of Prox1 in lymphatic endothelium rescued these phenotypes." (PMID 38915742, 2024). "More importantly, RNS in obesity regulate expression of VEGFR3 and Prox-1, suggesting that similar mechanisms may be responsible for our observation that aging decreases the expression of these molecules in LECs." (PMID 35821848, 2022). "Surprisingly, a small proportion of Prox1 + /− mice generated on the NMRI genetic background are capable of surviving to adulthood, but develop adult-onset obesity with weight gain noticeable at nine weeks of age." (PMID 32477160, 2020). "Obesity has not been reported in mice that are heterozygous for Prox1 specifically in the liver, pancreas, brain, or muscle." (PMID 32038308, 2020). "Prox1+/− and Tie2-Cre; Prox1+/f mice bred in the NMRI background develop obesity." (PMID 32038308, 2020). "In summary, based on the known roles of PROX1 in metabolic tissues we are tempted to speculate that PROX1 might be controlling certain aspects of obesity in non-lymphatic tissues." (PMID 32038308, 2020).
colorectal cancer (28 papers, 2010 to 2025). A primary or metastatic malignant neoplasm that affects the colon or rectum. "This was complemented by in vitro investigations of PROX1 in colorectal cancer (CRC), focusing on examining the effects of its loss or gain of function." (PMID 38244581, 2024). "High PROX1 expression was significantly associated with high-grade tumors and worse 5-year colorectal cancer-specific survival (CSS)." (PMID 35885529, 2022). "Contrary, in colorectal cancer, depletion of PROX1 in human hepatocellular carcinoma cell lines caused a significant increase in cell proliferation." (PMID 32370142, 2020). "In colorectal cancer, PROX1 plays an essential role in tumor progression; high immunohistochemical nuclear PROX1 expression is associated with poor patient outcome." (PMID 28854215, 2017). "An analysis of a large patient population revealed that high PROX1 expression was associated with poorly differentiated colorectal cancer and less favorable patient outcomes." (PMID 24797520, 2014). "Some studies reported PROX1 cytoplasmic expression by IHC staining in different tumor types, as in the case of colorectal cancer." (PMID 40660330, 2025). "Further research is needed to fully elucidate the mechanisms by which PROX1 contributes to lymphatic metastasis and to explore its potential as a therapeutic target or prognostic marker in colorectal cancer." (PMID 39328205, 2024). "Altering PROX1 expression in colorectal cancer (CRC) cells, which exhibit characteristics similar to stem cells, can impact tumor size and the population of stem cells." (PMID 38244581, 2024). "Prospero-related homeobox 1 (PROX1) is a homeobox transcription factor known to promote malignant transformation and stemness in human colorectal cancer (CRC)." (PMID 36594098, 2023). "Apart from the lymphatics, PROX1 is highly expressed in colorectal cancer tissue compared to background tissue samples." (PMID 35885529, 2022). "In the context of colorectal cancer, Prox1 was found to interact with the nucleosome remodeling and deacetylase (NuRD) complex to suppress Notch signaling, thereby allowing these cancer cells to maintain their stem cell properties and growth advantage." (PMID 33263009, 2020). "On the other hand, PROX1 promotes aggressive behavior of colorectal cancer, kaposiform hemangioendothelioma, glioma, and our last observations point to its distinct oncogenic role in follicular thyroid cancer (FTC)." (PMID 32370142, 2020). "Initially, we performed a ChIP-qPCR in HEPG2 hepatocellular carcinoma and SW620 colorectal carcinoma cell lines, transduced with Myc-tagged PROX1 expressing lentivirus." (PMID 29934628, 2018). "Separate studies, based on 643 European colorectal cancer patients, have shown that PROX1 is an important prognostic indicator for colorectal cancer-specific survival, further supporting that this regulation is clinically important." (PMID 27283988, 2016). "In this study, we describe a putative miR-205 binding site in the 3′UTR of PROX1, and we propose that this is a key mechanism behind the estrogen-mediated colorectal cancer-protective effect." (PMID 27283988, 2016). "Through mechanistic studies in multiple colorectal cancer cell lines, we show that ERβ upregulates miR-205, and that miR-205 targets and represses PROX1 through direct interaction with its 3′UTR." (PMID 27283988, 2016). "Prox1 was previously shown to promote dysplasia in colonic adenomas and colorectal cancer progression." (PMID 24069241, 2013). "We studied the prognostic value of immunohistochemical expression of PROX1 in a series of 517 patients with colorectal cancer (CRC)." (PMID 21970873, 2011). "Recently, PROX1 has been shown to promote tumour growth and malignant progression in colorectal cancers." (PMID 20052272, 2010). "Moreover, the involvement of PROX1 in epithelial–mesenchymal transition (EMT) engages it in the progression of colorectal cancer." (PMID 40843762, 2025).
colorectal cancer (continued). "Additionally, a different research team evaluated the predictive significance of PROX1’s IHC expression in 517 cases of colorectal cancer." (PMID 40660330, 2025). "Petrova and her colleagues recently showed that Prox1 promotes dysplasia in colonic adenomas and colorectal cancer (CRC) progression; loss of Prox1 does not prevent tumor initiation but instead impairs tumor progression." (PMID 23675176, 2010). "Specifically, in Colorectal Cancer (CRC), PROX1 is critical for instilling and preserving stem-cell-like attributes." (PMID 38244581, 2024). "However, the role of PROX1 in glucose metabolism remodeling in colorectal cancer (CRC) is unknown." (PMID 36594098, 2023). "We show that PROX1 is a potential target of miR-205 and that in clinical specimens from The Cancer Genome Atlas data, ERβ and miR-205 are decreased in colorectal cancer tissue compared to non-tumorous colon, while PROX1 levels are increased." (PMID 27283988, 2016). "The role of PROX1 in BC is not well described, but it belongs to a family of genes that drive cell invasion and PROX1 has been hypothesized to drive invasiveness in colorectal cancer and Kaposi sarcoma." (PMID 39478117, 2024). "Also, Erβ and miR-205 would reduce colorectal cancer compared to nontumorous colon, whole PROX1 level increases." (PMID 34691180, 2021).
hepatocellular carcinoma (24 papers, 2008 to 2025). A malignant tumor that arises from hepatocytes. "In more detail, there is much evidence suggesting that high PROX1 expression is associated with better prognosis and prolonged survival in cases of hepatocellular carcinoma." (PMID 40843762, 2025). "In line with patient data, Prox1 depletion caused hepatocyte fate loss in vivo and enabled the transition of hepatocellular carcinoma to cholangiocarcinoma." (PMID 39948437, 2025). "Conversely, in hepatocellular carcinomas, in pancreatic ductal adenocarcinomas, and in carcinomas of the biliary system, low PROX1 expression is associated with poor prognosis." (PMID 28854215, 2017). "In hepatocellular carcinoma, depletion of PROX1 causes a significant increase in cell proliferation, and patients with high PROX1 expression have better prognosis compared to patients with low expression." (PMID 27411302, 2016). "Further, Prox1 is required for cell proliferation of hepatoblasts during liver development, but loss of Prox1 from hepatocytes is associated with the development of hepatocellular carcinoma showing that Prox1 can play different roles at different developmental stages in a single organ system." (PMID 19023449, 2008). "Many studies have reported that PROX1 is involved in lymphangiogenesis and angiogenesis in some types of tumors, such as gastric cancer, oral squamous cell carcinoma and hepatocellular carcinoma." (PMID 40660330, 2025). "We have previously found that high levels of PROX1 in hepatocellular carcinoma (HCC) promote tumour growth and metastasis, and show poor prognosis and a high recurrence rate in HCC30,33." (PMID 36433955, 2022). "Related studies have shown that the expression of Prox1 in hepatocellular carcinoma is related to the degree of tumor differentiation." (PMID 34183992, 2021). "In a hepatocellular carcinoma cell line expressing high endogenous levels of PROX1, its silencing increased both MMP14 expression and MMP14-dependent invasion in 3D." (PMID 29934628, 2018). "There have been conflicting reports concerning the role of Prox1 in hepatocellular carcinoma, with some studies showing its oncogenic activity and some others suggesting it has tumor suppressive functions." (PMID 29371975, 2017). "In regard to carcinogenesis, Prox1 increased the expression of β-catenin, thus enhancing the proliferation of hepatocellular carcinoma." (PMID 29050214, 2017). "In colonic and hepatocellular carcinomas and in gliomas, the PROX1 staining is mainly nuclear, whereas in pancreatic cancer, mainly cytoplasmic staining is observed." (PMID 28854215, 2017). "Thus, PROX1 acts as a tumor suppressor in hepatocellular carcinoma, esophageal cancer, pancreatic cancer, oral cancer, hematologic malignancy, sporadic breast cancer, carcinoma of the biliary system, and papillary thyroid cancer (PTC)." (PMID 32370142, 2020). "It has been shown that the Myc-associated zinc finger protein (MAZ) may regulate the gene expression of Prox1 in hepatocellular carcinoma." (PMID 24503550, 2014). "Interestingly, PROX1 also contributes to tumor differentiation in hepatocellular carcinomas and pancreatic carcinoma." (PMID 25526434, 2014). "In addition, UCR41 is located upstream to PROX1, a gene that acts as a tumour suppressor in breast and pancreatic cancers, hepatocellular carcinomas and lymphomas." (PMID 20052272, 2010). "Upregulated PROX1 expression was significantly correlated with tumor differentiation, tumor size, metastasis, depth of invasion, and cancer stages in several human tumors, which include gastric cancer, hepatocellular carcinoma, esophageal squamous cell carcinoma, renal cell carcinoma." (PMID 40660330, 2025). "Furthermore, numerous investigations have found unusually high PROX1 expression in a variety of systemic malignant tumors, including neuroblastoma, colon cancer, kidney cancer, gastric cancer, esophageal squamous cell carcinoma, and hepatocellular carcinoma." (PMID 40660330, 2025).